SS18L2 (SS18 like 2)
Synonyms: KIAA-iso
Tractability: PROTAC: ubiquitination databases record sites on it.
Gene: Protein-coding gene on chromosome 3 (42,581,840 to 42,596,934, forward strand). Ensembl gene ENSG00000008324.
Subcellular location (Human Protein Atlas): Mitochondria; Nucleoli; Nucleoplasm
Gene Ontology:
Molecular function: protein binding
Genetic constraint (gnomAD): Loss-of-function variants: 5 observed, 7.42 expected, observed/expected ratio (o/e) 0.67, 90% interval 0.35 to 1.4. That is too few expected variants to judge how well the gene tolerates losing a copy. Missense variants: 84 observed, 90.19 expected, observed/expected ratio (o/e) 0.93, 90% interval 0.78 to 1.12. Synonymous variants: 39 observed, 34.66 expected, observed/expected ratio (o/e) 1.13, 90% interval 0.87 to 1.47.
Homologues: Orthologues: chimpanzee SS18L2 (100% identical), dog SS18L2 (95% identical), pig SS18L2 (95% identical), guinea pig SS18L2 (87% identical), mouse Ss18l2 (87% identical), rat Ss18l2 (87% identical), tropical clawed frog ss18l2 (66% identical), zebrafish ss18l2 (66% identical), Caenorhabditis elegans ZK973.9 (35% identical). Paralogues in human: SS18L1 (56% identical), SS18 (48% identical).
Diseases named in the same sentence as SS18L2 in open-access papers:
SS18L2 is named in the same sentence as 5 diseases in open-access papers, as found by Europe PMC text mining. Sharing a sentence is not in itself a finding about the gene and the disease. The quoted sentences say what the papers report.
lung carcinoma (1 paper, 2020). "A subset of the 11 gene signature has recently been reported in the context of lung cancer, either as an oncogenic driver (e.g. CD79B) or a prognostic marker (e.g. TRAF3IP3, SKAP2, and SS18L2)." (PMID 33287695, 2020).
synovial sarcoma (1 paper, 2022). "SS18L2 is the homolog of the SS18 gene, which is associated with chromosomal translocation characteristics of synovial sarcoma." (PMID 35973998, 2022). "However, the exact role of SS18L2 in synovial sarcoma or any other cancer is not known." (PMID 35973998, 2022).
cancer (2 papers, 2020 to 2022). A tumor composed of atypical neoplastic, often pleomorphic cells that invade other tissues. "The role of SS18L2 is not known in cancers and there is no study showing the effect of this gene in TNBC." (PMID 35973998, 2022).
infection (1 paper, 2023). The state of being infected such as from the introduction of a foreign agent such as serum, vaccine, antigenic substance or organism. "Similarly, SS18L2 mRNA was found to be upregulated in HIV-1 in early infection, as was found from the RNA profiling of CD4+ and CD8+ T cells in people living with HIV-1 versus those who were either nonprogressors or control HIV-1 negative groups." (PMID 37766271, 2023).
SS18L2 also shares sentences with these, for which no sentence is quoted: tumor (1 paper).